UFM1 (ubiquitin fold modifier 1)
Diseases named in the same sentence as UFM1 in open-access papers (continued):
Sharing a sentence is not in itself a finding about the gene and the disease.
ischemia (1 paper, 2021). A hypoperfusion of the BLOOD through an organ or tissue caused by a PATHOLOGIC CONSTRICTION or obstruction of its BLOOD VESSELS, or an absence of BLOOD CIRCULATION. "Higher expression of UFM1 in LEAD patients when compared to AAA subjects may reflect enhanced erythropoiesis stimulated by chronic ischemia characteristic for LEAD progression." (PMID 33801150, 2021).
leishmaniasis (1 paper, 2011). Infectious disease that is transmitted through the bite of hematophagous female phlebotomine sand flies. "Thus, Ufm1 conjugation pathway in Leishmania could be explored as a potential drug target in the control of Leishmaniasis." (PMID 21264253, 2011).
liver diseases (1 paper, 2023). "Nevertheless, this study sheds new light on theoretical and clinical researchers focusing on liver diseases by expanding our understanding of Ufm1 E3 ligase." (PMID 37131258, 2023). "Understanding the importance of the Ufm1 conjugate system, including its E3 ligase components and signaling effectors, may be important to the development of effective treatment strategies for liver disease in the future." (PMID 37131258, 2023).
nonalcoholic fatty liver disease (1 paper, 2024). "Similarly, in nonalcoholic fatty liver disease in mice, there’s an upregulation of DDRGK1, UFM1, and UFM1-conjugated DDRGK1, contributing to increased UFMylation expression." (PMID 38233375, 2024).
pancreatic cancer (1 paper, 2023). "Meanwhile, when UFSP2, the protease responsible for the cleavage of UFM1, was overexpressed, exactly same outcomes were observed in pancreatic cancer cells, which provides an additional line of evidence." (PMID 37280198, 2023). "RPL10 ufmylation was clearly observed in pancreatic cancer cells, whereas another ribosomal protein, RPS3, was unable to be modified by UFM1." (PMID 37280198, 2023). "To elucidate the process of RPL10 ufmylation involved in pancreatic cancer cells, we used immunoprecipitation to examine the interactions between co-substrates RPL10 and UFM1 as well as between RPL10 and E3 ligase UFL1, which could be similar to the ufmylating modifications of ASC1 and RPL26." (PMID 37280198, 2023).
spondyloepimetaphyseal dysplasia (1 paper, 2023). An osteochondrodysplasia that results in abnormalities of bone growth in the vertebral column, epiphysis, and metaphysis. "Mutations in most UFM1 pathway components have been linked to a type of bone pathology termed Sohat‐type spondyloepimetaphyseal dysplasia (SEMD)." (PMID 36680403, 2023).
steatosis (1 paper, 2023). Increased lipid within the cytoplasm of cells. "We observed increased expression of UFM1-conjugated proteins and ufmylation modification system components in livers with steatosis derived from NAFLD patients and NAFLD models." (PMID 37660122, 2023). "UFM1 and UFBP1 exhibited higher expression in livers with steatosis compared to non-steatosis samples." (PMID 37660122, 2023).
Stillbirth (1 paper, 2019). Death of the fetus in utero after at least 22 weeks of gestation. "We identified 12 genome-wide significant associations between these traits and genetic loci, including variants near CACNA2D3 with gestation length, MSRB3 and MSANTD1 with litter size, SMOC2 with cesarean section rate and UFM1 with stillbirth rate." (PMID 31263560, 2019).
thyroid cancer (1 paper, 2023). "To explore the role of ubiquitin-like proteins (ISG15, ATG8, FAT10, NEDD8, SUMO1, UFM1, URM1 and ATG12) in thyroid cancer, we integrated the datasets (GSE33630, GSE29265 and GSE76039) and analyzed 65 NT, 69 PTC and 40 ATC samples." (PMID 37501099, 2023).
viral infections (1 paper, 2025). "In particular, the role of several ubiquitin-like modifications in orthoflaviviral infection, such as NEDD8, FAT10, and UFM1, have yet to be described, although they do have roles in other viral infections." (PMID 40007042, 2025).
cancer (20 papers, 2014 to 2026). A tumor composed of atypical neoplastic, often pleomorphic cells that invade other tissues. "Among them, the Ub-fold modifier 1 (UFM1) is associated with several important functions, even cancer." (PMID 31597257, 2019). "Furthermore, aberrant UFM1 cascades are reportedly associated with several human diseases, such as cancer, ischemic heart disease, diabetes, atherosclerosis, hip dysplasia, and schizophrenia." (PMID 37947621, 2023). "Herein, we summarize the process and functions of UFM1 modification, illustrating the relationship and mechanisms between aberrant UFMylation and diversified tumors, aiming to provide novel diagnostic biomarkers or therapeutic targets for cancer treatments." (PMID 35884562, 2022). "In addition, an abnormal UFM1 cascade is implicated in a variety of diseases, including diabetes, heart failure, inflammatory disease, liver development, hip dysplasia, cancer and brain development." (PMID 35884562, 2022). "In some cancers, the UFM1 machinery is dysregulated – sometimes turned down, other times up – in ways that help cancer cells cope with stress or, if disrupted, can hinder tumor growth." (PMID 41065375, 2025). "Unraveling the regulatory mechanism by which the UFM1 system modulates the efficiency of antigen presentation has the potential to enhance immune surveillance against microorganism infections and even cancer cells." (PMID 39259506, 2024). "UFMylation stabilizes SALC7A11 and metformin reduces SLC7A11 protein stability by inhibiting UFM1 expression, which induces ferroptosis to suppress cancer proliferation." (PMID 37947621, 2023). "Inhibiting PD-L1 UFMylation by silencing UFL1 or UFM1, or by the defective UFMylation of PD-L1, stabilized PD-L1 in multiple human and murine cancer cells and undermined antitumor immunity both in vitro and in mice." (PMID 37947621, 2023). "This article aims to improve our understanding of UFM1 modification, as well as provide some new strategies for cancer treatment." (PMID 35884562, 2022). "The results showed that overexpression of UFM1 effectively blocked the anti-cancer effect of metformin and restored the inhibition of the GSH level mediated by metformin." (PMID 34162423, 2021). "Since UBA5 is very important for the UFM1 protein conjugation in erythroid development and for promoting proliferation and survival of cancer cells, this enzyme is considered as a therapeutic target for disrupting cancer progression." (PMID 31597257, 2019). "It has been shown that components of the Ufm1 cascade are upregulated under ER stresses in multiple cancer cell lines." (PMID 24921187, 2014). "Additionally, abnormal stress adaptations of the UFM1 conjugation system contribute to the pathophysiological complications of inflammatory diseases and cancer, underscoring its significance as a key regulatory node in human health and disease." (PMID 41823810, 2026). "Conversely, in contexts where UFM1 might be helping cancer cells survive therapy-induced stress, carefully dampening its activity could sensitize those cells to treatment." (PMID 41065375, 2025). "Additionally, we assess the potential of these findings to support the development of new therapeutic interventions targeting the UFM1 system, with potential applications in inflammatory diseases, infections and even cancer therapy." (PMID 39259506, 2024). "Most knowledge about UFM1 substrates is derived from studies in cancer cell lines." (PMID 38903110, 2024). "In summary, our results showed that metformin might exert its anti-cancer effect through UFM1, which can regulate the GSH level." (PMID 34162423, 2021).
cancer (continued). "For example, loss of UFM1’s deconjugating enzyme UFSP2 can accelerate cell proliferation in colon cancer, while overexpression of UBA5 (the E1) in certain tumors might allow cancer cells to survive ER stress in the tumor environment." (PMID 41065375, 2025). "In addition, whether the UFM1 cascade could be a potential therapeutic target for cancer diagnosis and treatment remains unknown." (PMID 35884562, 2022). "In addition, we identified SLC7A11 as a new UFMylation substrate and found that targeting the UFM1/SLC7A11 pathway could be a promising cancer treatment strategy." (PMID 34162423, 2021). "We speculated that UFM1 might play a certain role in the anti-cancer effect of metformin." (PMID 34162423, 2021). "Amplification, deletion or mutation of genes encoding the UFMylation factors (UBA5, UFC1, UFL1, UfSP2 and UFM1) has been detected in malignant tumors from various tissues and organs in the TCGA database, indicating that UFMylation may promote or suppress tumorigenesis in different cellular contexts." (PMID 30783677, 2019). "It has been reported that most of the 8 ARGs (VIM, UFM1, TSC2, SRC, MEFV, CTTN, CFTR and CDKN1A) are related to cancer." (PMID 35121801, 2022). "A comprehensive analysis of genomic alterations in the eight UFMylation family genes (UFM1, UBA5, UFC1, UFL1, UfBP1, CDK5RAP3, UfSP1, and UfSP2) across the TCGA database of 33 cancer types identified 55 recurrent and focal somatic copy number alteration events in UFMylation family genes." (PMID 37947621, 2023). "This discrepancy could be attributed to the fundamental differences between non-proliferating neurons and proliferating cancer cells, further highlighting the need to study the UFM1 pathway in neurons and in the brain." (PMID 38903110, 2024). "Mechanistically, the anti-cancer effect of metformin was achieved by inhibiting the UFMylation of SLC7A11, a cysteine transporter critical for ferroptosis, implying that targeting the UFM1/SLC7A11 pathway could be a promising cancer treatment strategy." (PMID 35884562, 2022). "However, the physiological and pathological roles of UFM1 modification in different types of cancers are not completely understood." (PMID 35884562, 2022).
tumor (14 papers, 2013 to 2025). "Herein, we review the current literature and elucidate the role and underlying mechanisms, shedding light on the impact of the UFM1 conjugation system on tumor development." (PMID 35884562, 2022). "Upregulation of UFM1 inhibits migration and invasion abilities In vivo study further identified the tumor suppressive function of UFM1." (PMID 39247188, 2024). "Combining the low CDK5RAP3 and UFM1 expression, analysis of related factors showed that the low expression level of the two was related to tumour size, depth of invasion, lymph node metastasis and TNM staging." (PMID 36387125, 2022). "Subsequently, the related protein expression levels (proteins were extracted from subcutaneous tumor tissues) of the UFM1 overexpression group was consistent with the conclusions obtained from cell experiments." (PMID 31533855, 2019). "After overexpression of UFM1, tumor growth was inhibited, and the growth of tumor volume was significantly decelerated compared with the control group." (PMID 31533855, 2019). "In vivo study further identified the tumor suppressive function of UFM1 in nude mouse model." (PMID 39247188, 2024). "Moreover, treatment with sunitinib, targeting multiple tyrosine kinases, significantly reduced UFMylation levels, while upregulation of active UFM1 was found to partially counteract the anti-tumor effects of sunitinib." (PMID 39247188, 2024). "Overall, targeted therapy against the UFM1 system could be a complementary approach to existing PD‐1/PD‐L1‐based tumour immunotherapy." (PMID 39259506, 2024). "Upregulation of active UFM1 partially counteracts the anti-tumor effects of sunitinib." (PMID 39247188, 2024). "In light of this aspect, we aim to present an overview of how the UFM1 system impacts adaptive immunity, including the development and function of B cells, PD‐1/PD‐L1 checkpoint‐mediated anti‐tumour immune responses, and the HLA‐I‐mediated antigen presentation pathway." (PMID 39259506, 2024). "Additionally, the western blot results of 8 pairs of samples showed that the UFM1 expression in tumor tissues was significantly lower than that in adjacent tissues." (PMID 34721576, 2021). "CCK-8 assay further indicated that the suppression of miR-934 alleviated cell viability, while the downregulation of UFM1 could reverse this effect (∗P < 0.05), which indirectly suggested that UFM1 was a tumor suppressor in HCC cells." (PMID 34721576, 2021). "UFM1 has been found to be involved in the regulation of tumor development." (PMID 31533855, 2019). "The modulation of the UFM1 system presents an innovative therapeutic strategy, which could help reduce PD‐1/PD‐L1 expression and, consequently, enhance the ability of the immune system to target and kill tumour cells." (PMID 39259506, 2024). "Based on the univariate analysis, overall survival was related to BMI, tumour size, TNM staging and combined CDK5RAP3 and UFM1 expression." (PMID 36387125, 2022). "The UFMylation of SLC7A11 is detected by immunoprecipitation and the expression of UFM1 and SLC7A11 in tumor tissues was detected by immunohistochemical staining." (PMID 34162423, 2021). "Recent studies indicate that DDRGK1 interacts with a protein complex containing UFL1 (UFM1-specific ligase 1), the putative tumor suppressor LZAP/C53 and UFM1 (ubiquitin fold modifier 1), and both UFL1 and LZAP/C53 have a regulatory role in the NF-κB pathway." (PMID 23675531, 2013).
infection (6 papers, 2014 to 2025). The state of being infected such as from the introduction of a foreign agent such as serum, vaccine, antigenic substance or organism. "In both cases, UFL1 and UFM1 localised to S. flexneri, suggesting a broad and conserved role during infection." (PMID 40501833, 2025). "Microscopy experiments validated the localisation of UFL1 and UFM1 to the surface of S. flexneri during infection in HeLa cells, using both HA-tagged exogenous expression and antibodies against the endogenous proteins." (PMID 40501833, 2025). "Together, these results indicate that the S. flexneri T3SS effector IpaH9.8 interacts with UFM1 to delay UFMylation of the bacterial surface during infection." (PMID 40501833, 2025). "We observed a strong decrease in zebrafish larvae survival during infection upon depletion of ufm1 and ufl1, both in the case of S. flexneri and S. Typhimurium." (PMID 40501833, 2025). "Macroscopic examination, the representative images of whole livers showing reduction in UFM1 liver tumor burden after infection with UFM1 compared to infection with control." (PMID 31533855, 2019). "The limited UFM1 decoration of S. flexneri during infection led us to hypothesise that additional bacterial effectors may intersect with the UFMylation cascade beyond UFL1 recruitment." (PMID 40501833, 2025). "While deletion of ipaH9.8 did not affect UFL1 recruitment to S. flexneri, we observed a higher decoration of UFM1 in S. flexneri ΔipaH9.8 compared to WT at 3 hours post infection (2.6 ± 0.5-fold), which further increased (4.4 ± 0.6-fold) in the case of the double mutant ΔrfaCΔipaH9.8." (PMID 40501833, 2025). "Here, we demonstrate that the UFMylation system, a post-translational modification pathway that catalyzes the transfer of UFM1 onto proteins and promotes infection by multiple orthoflaviviruses, including dengue virus (DENV), Zika virus (ZIKV), West Nile virus, and yellow fever virus." (PMID 40459261, 2025). "In addition, several putative protease-coding genes, including UFM1- and sentrin-specific proteases and serine-type peptidases, were identified as upregulated during the beginning of the parasitoid infection." (PMID 30333799, 2018). "Our work has shown that both UFL1 and its substrate peptide UFM1 are recruited to the surface of S. flexneri and S. Typhimurium during infection, which showed little to no overlap with bacterial ubiquitylation." (PMID 40501833, 2025). "At later timepoints (5 hours post infection) the levels of UFM1 decoration were higher and non-significantly different for S. flexneri WT, ΔipaH9.8 and the double mutant ΔrfaCΔipaH9.8 (37.8% ± 30.6%, 54.6 ± 26.7%, 60.6% ± 12.1%, respectively)." (PMID 40501833, 2025). "The S. flexneri surface became UFMylated during infection, as bacteria recovered from infected cells presented UFM1-conjugates absent in bacteria from broth." (PMID 40501833, 2025). "We observed that UFL1 and UFM1 were also recruited to the surface of S. Typhimurium at 3 hours post infection, indicating that bacterial UFMylation is not a phenotype exclusive to S. flexneri." (PMID 40501833, 2025).
degenerative diseases (2 papers, 2024 to 2025). "Recent studies have connected the UFM1 system to the handling of proteins implicated in adult-onset neurodegenerative diseases." (PMID 41065375, 2025). "Defects in UFM1 signaling cause neurodevelopmental and degenerative diseases, highlighting its essential role in proteostasis." (PMID 41065375, 2025). "If enhancing UFMylation can improve a cell’s ability to handle misfolded proteins, one might envision therapies to boost the UFM1 pathway in neurodegenerative diseases or aging-related proteostasis decline." (PMID 41065375, 2025).
bacterial infection (1 paper, 2025). "Other Ubls such as FAT10 and UFM1 interface with bacterial infection, though specific effectors that manipulate these processes have yet to be identified." (PMID 41358638, 2025).
immune disorders (1 paper, 2024). "In this review, we concentrate on the newly uncovered principles of the UFM1 system's involvement in both innate and adaptive immunity, the immune disorders directly linked to defective UFMylation, and the potential roles in the crosstalk between the endocrine system and immune responses." (PMID 39259506, 2024).
neurodevelopmental disorder (1 paper, 2021). A behavioral and cognitive disorder with onset during the developmental period that involves impaired or aberrant development of intellectual, motor, or social functions. "For example, genetic screening revealed the participation of UFM1 enzymes in several neurodevelopmental disorders ranging from infantile encephalopathy, microencephaly, and ataxia." (PMID 33578803, 2021).
UFM1 also shares sentences with these, for which no sentence is quoted: leukodystrophy (4 papers); cardiac disease (2); Failure to thrive (2); intellectual deficiency (2); liver fibrosis (2); neurological diseases (2); schizophrenia (2); age (1); autism (1); Cirrhosis (1); colon cancer (1); emphysema (1); heart (1); heart failure (1); hypertrophy (1); Lewy body disease (1); movement disorder (1); myeloid leukemia (1); osteosarcoma (1); pancreatic adenocarcinoma (1); peritonitis (1); skeletal dysplasia (1); tauopathies (1).